U8 (U8 small nucleolar RNA )
Synonyms: LOC124900406
Gene: Small nucleolar RNA gene on chromosome 18 (58,818,883 to 58,819,016, reverse strand). Ensembl gene ENSG00000199713.
Gene Ontology:
Biological process: RNA processing
Cellular component: nucleolus
Homologues: Orthologues: chimpanzee U8 (99% identical), macaque U8 (90% identical), guinea pig U8 (82% identical). Paralogues in human: U8 (86% identical), U8 (85% identical), U8 (84% identical), U8 (83% identical), U8 (81% identical), U8 (80% identical), U8 (79% identical), U8 (78% identical), U8 (76% identical), U8 (72% identical), U8 (65% identical), U8 (52% identical).